CRABP2 (cellular retinoic acid binding protein 2)
Diseases named in the same sentence as CRABP2 in open-access papers (continued):
Sharing a sentence is not in itself a finding about the gene and the disease.
colon adenocarcinoma (2 papers, 2025). "Notably, Kaplan–Meier survival curve analysis revealed that increased CRABP2 expression was significantly predictive of poorer overall survival (OS) in non‐metastatic TCGA‐colon adenocarcinoma/rectal adenocarcinoma (COADREAD) patients (p = 0.048)." (PMID 40305785, 2025). "We first compared the expression of five CRBPs—retinol‐binding protein 1 and 2 (RBP1/2), CRABP1, CRABP2, and FABP5—in normal (N) versus tumor (T) tissues in The Cancer Genome Atlas (TCGA)‐Colon Adenocarcinoma (COAD) dataset." (PMID 40305785, 2025).
cutaneous melanoma (2 papers, 2023 to 2025). A primary melanoma arising from atypical melanocytes in the skin. "This study found that negative correlations of CRABP2 and immune checkpoint markers (PD-1, PD-L1, and CTLA-4) were observed in breast invasive carcinoma (BRCA), skin cutaneous melanoma (SKCM), stomach adenocarcinoma (STAD) and testicular germ cell tumors (TGCT)." (PMID 38186580, 2023).
liver cancer (2 papers, 2021 to 2024). An epithelial or non-epithelial malignant neoplasm that arises from the liver. "The expression level of CRABP2 in liver cancer tissue increases with tumor progression, and inhibiting the expression of CRABP2 can suppress the proliferation, migration, and invasion of tumor cells in vitro." (PMID 38195606, 2024). "CRABP2 is highly expressed in poorly differentiated liver cancer, knocking down CRABP2 can inhibit the proliferation, migration, and invasion of liver cancer cell lines, promote cell apoptosis, and reduce the expression of ERK/VEGF pathway-related proteins." (PMID 34632074, 2021).
malignant glioma (2 papers, 2021 to 2025). A grade III or grade IV glioma arising from the central nervous system. "In malignant gliomas, the median ratio of FABP5/CRABP2 mRNA expression of 3.6 in short-term survivors (≤6 months) was significantly higher than that of long-term survivors (≥36 months) of 1.4, indicating that the FABP5/CRABP2 ratio can determine the direction of cell differentiation." (PMID 34632074, 2021).
meningioma (2 papers, 2023 to 2025). A generally slow growing tumor attached to the dura mater. "Specifically, NF2 meningiomas expressed higher levels of arachnoid CLDN11 and pial LAMA2, while TRAF7 tumors overexpressed dural MGP and dural/arachnoid CRABP2 relative to NF2 tumors." (PMID 36937440, 2023).
retinoblastoma (2 papers, 2020 to 2024). A malignant tumor that originates in the nuclear layer of the retina. "Elevated CRABP2 mRNA transcript levels were observed in retinoblastoma tissue compared with normal retinal tissue, and infiltrating retinoblastoma showed elevated levels of CRABP2." (PMID 38915108, 2024). "Similarly, higher CRABP2 expression corresponded to invasive retinoblastomas and poorer prognosis in estrogen receptor-negative breast cancer." (PMID 32560331, 2020).
triple-negative breast carcinoma (2 papers, 2015 to 2021). An invasive breast carcinoma which is negative for expression of estrogen receptor (ER), progesterone receptor (PR), and human epidermal growth factor receptor 2 (HER2). "We propose that these three RA-binding proteins can serve as biomarkers for predicting triple-negative breast cancer response to RA, with elevated levels of either cytoplasmic CRABP1 or FABP5 associated with RA resistance, and elevated levels of nuclear CRABP2 associated with sensitivity to RA." (PMID 26142905, 2015).
acne (1 paper, 2023). An inflammatory process of the sebaceous glands which is characterized by comedones, nodules, papules and/or pustules on the skin. "Indeed, increased expression of ATRA-induced CRABP-2 and TRAIL have been demonstrated in the basal and suprabasal layers of sebaceous glands and skin during isotretinoin treatment of acne patients, where increased isotretinoin-mediated apoptosis activity has been observed." (PMID 36585988, 2023).
anaplastic thyroid cancer (1 paper, 2019). "Resveratrol effectively reverses RA tolerance and upregulates CRABP2 expression of anaplastic thyroid cancer cell line THJ-11T." (PMID 31736873, 2019). "The finding of recovered CRABP2 expression in resveratrol-treated anaplastic thyroid cancer cells has encouraged us to investigate the possible demethylating capacity of this polyphenol agent." (PMID 31736873, 2019).
Arthritis (1 paper, 2018). Inflammation of a joint. "The increase was observed 7 to 18 days after injection in the K/BxN serum transfer model, a time span including the peak of inflammation at 9 days and the phase of resolution, which could indicate a role of Crabp2 in the auto-limitation of arthritis." (PMID 29880835, 2018). "Potentiation of Fas-induced apoptosis by CRABP2 silencing could be of clinical interest because it persisted in the presence of TNFα and IL1β, two pro-inflammatory stimuli that are present in arthritis and that increase RA FLS survival." (PMID 29880835, 2018). "However, the potentiation of Fas induced apoptosis observed after suppression of CRABP2 that persists in spite of an inflammatory cytokines makes of this molecule a potential drug target worth of study in additional preclinical models of arthritis." (PMID 29880835, 2018). "In accordance with these differential effects, it has been observed that the pro-apoptotic or pro-survival role of retinoic acid correlates with the CRABP2/FABP5 ratio in a variety of cells, making it possible that modulation of this pathway could have impact in arthritis." (PMID 29880835, 2018).
clear cell renal cell carcinoma (1 paper, 2023). "In addition, CRABP2 was also differentially expressed as an immune related gene in clear cell renal cell carcinoma and was associated with poor prognosis." (PMID 38186580, 2023).
dermatitis (1 paper, 2013). An inflammatory process affecting the skin. "Notably, in our mouse model, the Fabp5 vs. Crabp2 ratio was increased in allergen-induced dermatitis." (PMID 23977003, 2013). "Furthermore, the increased ratio of Fabp5 vs. Crabp2 may indicate an up-regulation of the PPARδ pathway in allergen-induced dermatitis in addition to the altered RAR signaling." (PMID 23977003, 2013). "Notably, the ratio of Fabp5 vs. Crabp2 gene expression, both delivering ATRA to their respective cognate receptors, significantly increased in allergen-induced dermatitis." (PMID 23977003, 2013).
endometrial tumours (1 paper, 2020). "Crabp2 expression was upregulated in endometrial tumours from rats fed an HFD." (PMID 32927694, 2020).
esophageal tumor (1 paper, 2016). "In line with above results, the triplicate data from colony formation assays showed that CRABP2 indeed remarkably suppressed the esophageal tumor cell growth." (PMID 26839961, 2016). "In the study, using the CCK8 kit and the colony formation assays, we proved that CRABP2 remarkably inhibited the cell growth of esophageal tumor cells in vitro." (PMID 26839961, 2016). "Data from wound-healing and transwell assays showed that overexpression of CRABP2 greatly blocked esophageal tumor cell metastasis." (PMID 26839961, 2016). "Clinical characterization of CRABP2 expression in paired esophageal tumor tissues and adjacent normal tissues." (PMID 26839961, 2016). "As a result, we speculated that CRABP2 acted as a tumor suppressor in esophageal tumor tissues due to the high CRABP2/FABP5 ratio." (PMID 26839961, 2016). "Thirdly, CRABP2 negatively regulates cell metastasis of esophageal tumor cells via EMT." (PMID 26839961, 2016). "Therefore, in the study, we evaluated the role of CRABP2 in cell metastasis in esophageal tumor cells." (PMID 26839961, 2016). "The subsequent Hoechst 33342 staining and flow cytometry assays showed that CRABP2 could obviously induced apoptotic cell death of esophageal tumor cells." (PMID 26839961, 2016). "Additionally, further tumor-bearing nude mice experiments confirmed that CRABP2 in esophageal tumor cells could significantly suppress the cell proliferation in vivo." (PMID 26839961, 2016).
head and neck carcinoma (1 paper, 2024). A carcinoma that arises from the head and neck region. "In addition, an article published in 2009 revealed that the absence of CRABP2 is closely related to low survival rate of head and neck carcinoma, suggesting the anticancer role of CRABP2." (PMID 38807101, 2024).
oral cancer (1 paper, 2024). "Since the role of CRABP2 in oral cancer is controversial, more experiments should be conducted in the future for further exploration." (PMID 38807101, 2024).
oral candidiasis (1 paper, 2022). Infection of the mucosal lining of the mouth with the fungus Candida albicans. "Also, the expression of MMP1, MMP10, COL5A2, SERPINB4, and CRABP2 was increased under both conditions, confirming that oral candidiasis may drive OSCC progression events in vivo." (PMID 35089096, 2022).
oropharyngeal squamous cell carcinoma (1 paper, 2024). "CRABP2 has been reported to be downregulated in human papillomaviruses-positive oropharyngeal squamous cell carcinoma by Martinez in 2007." (PMID 38807101, 2024).
osteonecrosis (1 paper, 2021). A none disease characterized by death of bone tissue due to a lack of blood supply. "Moreover, overexpression of CRABP2 delayed the progression of DEX-induced osteonecrosis of the femoral head (ONFH) animal model." (PMID 33879199, 2021).
skin tumor (1 paper, 2024). "During the processes of developmental morphogenesis, adult hair follicle cycling, and skin tumor formation, CRABP1 and CRABP2 are dynamically regulated." (PMID 39457415, 2024).
Stroke (1 paper, 2016). Sudden impairment of blood flow to a part of the brain due to occlusion or rupture of an artery to the brain. "Our data are consistent with transcription profiling of stroke tissue from rat showing up-regulation of both Raldh2 and CRABP2 in the ischemic hemisphere following injury." (PMID 27422020, 2016).
uterine fibroids (1 paper, 2024). "The expression level of CRABP2 in uterine fibroids is significantly higher than that in normal uterine smooth muscle, and estrogen can promote the expression of CRABP2, suggesting that CRABP2 plays an important role in the occurrence of uterine fibroids." (PMID 38195606, 2024).
uveal melanoma (1 paper, 2025). A melanoma derived from melanocytes of the uveal tract. "Similarly, in uveal melanoma (UVM) and liver hepatocellular carcinoma (LIHC), CRABP2 expression is significantly correlated with seven of these immune checkpoint genes (LAG3, CTLA4, PDCD1LG2, HAVCR2, PDCD1, CD274, and TIGIT)." (PMID 39991584, 2025).
tumor (48 papers, 2015 to 2025). "While cellular retinoic acid binding protein 2 (CRABP2) has been implicated in tumor progression, metastasis and drug resistanceacross multiple cancer types, its functional role and molecular mechanisms of CRABP2 in NSCLC progression remain largely unexplored." (PMID 40657374, 2025). "High CRABP2 expression is associated with advanced tumour stage, reduced overall survival, and enriched expression in peritoneal metastatic lesions." (PMID 41149452, 2025). "Among these, cellular retinoic acid‐binding protein 2 (CRABP2) has been implicated as both a tumor activator and suppressor." (PMID 40305785, 2025). "High CRABP2 expression is also associated with poor tumour differentiation, increased recurrence, and significantly reduced overall survival." (PMID 41149452, 2025). "Univariate analysis showed that tumor diameter, surgical type, tumor differentiation, pT stage, pN stage, pTNM stage, lymphovascular invasion, and CRABP2 expression were associated with OS in GC patients (all P < 0.05)." (PMID 36195596, 2022). "Since NF1 deficient tumor cells are generally characterized by over-activation of Ras and, as we demonstrated, by CRABP2 expression, the combination of MEKi and ATRA seems to be a promising new approach, necessarily to be validated in animal experiments." (PMID 29131833, 2017). "Higher CRABP2 levels were found to be associated with recurrence in three cohorts of tumor tissues." (PMID 30696915, 2019). "Together, these findings identify the AFG3L2–SLC25A39 axis as a mechanism by which cytoplasmic CRABP2 promotes tumor progression in CRC cells." (PMID 40305785, 2025). "CRABP2 promotes the G2/M phase transition of LUAD tumor cells, inhibits apoptosis, and additionally plays a role in regulating the immune microenvironment." (PMID 39991584, 2025). "CRABP2 demonstrates variable roles in gastrointestinal (GI) cancers, functioning either as a tumour suppressor or as a promoter depending on cancer type and molecular context." (PMID 41149452, 2025). "To verify the significance of CRABP2 in the tumor immune microenvironment, we used the CIBERSORT algorithm to evaluate the presence of 22 distinct immune cell types in LUAD samples." (PMID 39991584, 2025). "In vivo, CRABP2 knockdown reduces tumour growth and angiogenesis, indicating that CRABP2 promotes HCC progression through survival and pro-metastatic signalling." (PMID 41149452, 2025). "In mouse models and CRC cell lines, CRABP2 knockout markedly reduced tumour burden, increased apoptosis, and suppressed Ki-67 expression, highlighting its tumour-promoting function." (PMID 41149452, 2025). "It indicates that the low expression of CRABP2 will promote the recruitment of immune effector cells and reduce the proportion of immunosuppressive cells, thus playing a role in tumor inhibition in LUAD." (PMID 39991584, 2025). "In summary, our research has confirmed that CRABP2 expression is elevated in the plasma of patients with early-stage (IA) LUAD as well as in the tumor tissues of patients with intermediate and advanced-stage LUAD." (PMID 39991584, 2025). "Using patient-derived xenograft (PDX) models, the authors showed that CRABP2 silencing enhances the anti-tumour effects of oxaliplatin." (PMID 41149452, 2025). "We then performed immunohistochemistry evaluating CRABP2 protein expression in 128 tissue microarray samples to assess correlation with the Tumor‐Node‐Metastasis (TNM) stage." (PMID 40305785, 2025). "In tumours with AKT1E17K/TRAF7 mutations, specific antibodies were available for four up-regulated proteins (CLIC3, CRABP2, GMDS, and Pyruvate carboxylase)." (PMID 40562609, 2025). "Data from CPTAC indicated that the protein expression of CRABP2 were also elevated in cancerous tissue from 111 LUAD patients when contrasted with adjacent non-tumor samples." (PMID 40657374, 2025). "Kaplan–Meier survival analyses further indicate that CRABP2 primarily promotes tumor progression in non‐metastatic stages, leading to worse prognoses." (PMID 40305785, 2025).
tumor (continued). "High CRABP2 expression also correlates with immunosuppressive tumour microenvironments, marked by low CD8+ and CD4+ T cell infiltration and enrichment of M2 macrophages." (PMID 41149452, 2025). "The findings suggest that the low expression of CRABP2 will promote the recruitment of immune effector cells and reduce the proportion of immunosuppressive cells, thus playing a role in tumor inhibition in LUAD." (PMID 39991584, 2025). "Our findings further support a correlation between CRABP2 and immune cells within the tumor microenvironment." (PMID 39991584, 2025). "On one hand, nuclear CRABP2 promotes tumour growth by enhancing proliferation and suppressing apoptosis through direct interaction with the tumour suppressor retinoblastoma protein (RB1)." (PMID 41149452, 2025). "We found that liensinine aggravated tumor growth when administered in combination with CRABP2‐Mut‐NLS overexpression, with consistent results observed in vitro." (PMID 40305785, 2025). "Functionally, knockdown of CRABP2 inhibited NSCLC cell proliferation, migration, and invasion, and lipid droplet accumulation in vitro, while CRABP2 targeting inhibited tumor growth, lipid droplet content and metastasis in xenograft model." (PMID 40657374, 2025). "In HCC, CRABP2 seems to function as tumour promoter as it is significantly upregulated in tumour tissues and cell lines, correlating with disease progression." (PMID 41149452, 2025). "In colorectal cancer (CRC), CRABP2 is significantly upregulated in tumour tissues compared to normal epithelium and its role appears to be even more complicated." (PMID 41149452, 2025). "Alterations in CRABP2 expression or copy number can influence the tumor microenvironment, potentially playing a significant role in the onset, metastasis, and immune response of LUAD." (PMID 39991584, 2025). "In contrast, CRABP2 is markedly upregulated in oxaliplatin-resistant tumours and functions as a mediator of chemoresistance." (PMID 41149452, 2025). "CRABP2 displays a dual and compartmentalised role, influencing both tumour growth and metastasis through distinct nuclear and cytoplasmic mechanisms." (PMID 41149452, 2025). "CRABP2 exerts these effects by modulating diverse biological processes in tumor cells, including proliferation, apoptosis, invasion, migration, and angiogenesis." (PMID 40305785, 2025). "In summary, we validated five highly expressed proteins as specific targets for different tumour mutational backgrounds: CLIC3, CRABP2, and GMDS for AKT1E17K/TRAF7 tumours, CD44 for KLF4K409Q/TRAF7 tumours and ANXA3 for NF2−/− tumours." (PMID 40562609, 2025). "Immunohistochemistry (IHC) of the excised tumor sections, which verified the correlation between proliferation and RanGAP1, indicated that the CRABP2 expression levels in RanGAP1 knockdown tumor tissues were observably lower." (PMID 38267624, 2024). "In order to verify the effect of CRABP2 on tumor drug sensitivity in vivo, we constructed corresponding mouse models." (PMID 38195606, 2024). "CRABP2 and HMGA2 had the highest expression in ChRCCdediff and have been previously implicated in tumor aggressiveness and EMT." (PMID 38775158, 2024). "This study unveils a novel perspective on the involvement and importance of CRABP2 in tumor immunotherapy, particularly highlighting its role in controlling the infiltration of CAFs and the immune response in SKCM." (PMID 38186580, 2023). "The Kaplan-Meier plotter website was used to analyze the relationship between the expression level of CRABP2 and prognosis in tumor patients receiving ICIs." (PMID 38186580, 2023). "The associations of mRNA expression between CRABP2 and three immune checkpoint molecules (PDCD1, CD274 and CTLA4) were examined in 33 different tumor types from the TCGA database using the TIMER2.0 and Xiantao tools." (PMID 38186580, 2023).